DLL4 (delta like canonical Notch ligand 4)
Diseases named in the same sentence as DLL4 in open-access papers (continued):
Sharing a sentence is not in itself a finding about the gene and the disease.
tumor (continued). "Further, certain xenografts that are resistant to anti-VEGF therapy are reported to be sensitive to anti-Dll4 and combination treatment with anti-VEGF and anti-Dll4 has additive inhibitory effects on tumor growth." (PMID 20569499, 2010). "Although blocking Dll4 appears to promote angiogenesis, the neovasculature is functionally abnormal and it cannot support tumor cell survival." (PMID 20414463, 2010). "A further important pathway in angiogenesis is the recently identified Delta-Notch pathway, and particularly the ligand Delta-like 4 (Dll4), was identified as a new target in tumor angiogenesis." (PMID 20569499, 2010). "In contrast, a significant decrease in tumor growth was observed in RT2 Dll4+/- mice when compared to the RT2 Dll4+/+ control group." (PMID 21092311, 2010). "Similar levels of endothelial Dll4 expression were observed in the centre of the tumour and at the invading edge." (PMID 19844231, 2009). "Genetic or pharmacological disruption of Dll4-Notch signaling leads to excessive tip-cell formation and vessel sprouting in cultured cells, in zebrafish and mouse embryos, and during tumor angiogenesis." (PMID 20016694, 2009). "Dll4 is a key player in the Notch signalling pathway known to regulate tumour angiogenesis, as does Cxcl5, and growth." (PMID 19194513, 2009). "Conversely, Dll4 activation of endothelial Notch signaling reduces tumor angiogenesis, but increases vessel diameter and perfusion, which enhances tumor growth." (PMID 20016694, 2009). "Recently, the Delta-Notch pathway, and particularly the ligand Delta-like 4 (Dll4), was identified as a new target in tumour angiogenesis." (PMID 18827808, 2008). "For example, in human tumours, Dll4 expression was localised to the blood vessels of clear-cell renal tumours and was at nine-fold higher levels than in normal kidney tissue." (PMID 18827808, 2008). "One particular ligand, Dll4, was recently identified as a potentially important new target in tumour angiogenesis." (PMID 18827808, 2008). "Increased expression of Dll4 in tumour vessels has been reported in several mouse tumour models and in human tumours." (PMID 18827808, 2008). "For example, Dll4 expression was found to be particularly strong on the growing front of vessels as tumours become vascularised." (PMID 18827808, 2008). "For example, blockade of VEGF in tumour-bearing mice results in a rapid and profound reduction of Dll4 expression by the tumour blood vessels." (PMID 18827808, 2008). "Studies of tumours in mice and humans have shown that Dll4 is strongly expressed in tumour blood vessels compared to adjacent normal vessels." (PMID 18827808, 2008). "Several studies have documented the expression of Notch components in tumour vessels, most notably Dll4." (PMID 18827808, 2008). "An exciting opportunity has arisen because recent studies have shown that blockade of Dll4 can have potent antitumour effects on tumours that are resistant to VEGF inhibition." (PMID 18827808, 2008). "Conversely, blockade of VEGF in tumours resulted in a rapid decrease of Dll4 expression in tumour vessels, showing that a significant portion of the Dll4 expression in the growing tumour vessels requires ongoing VEGF signalling." (PMID 18827808, 2008). "Tumor-infiltrated MDSCs and tumor burden were significantly reduced in the DLL4-KO group." (PMID 41326912, 2025). "IFN-γ can hinder tumor angiogenesis through targeting the Notch-Dll4/Dll1 pathways or integrins." (PMID 40370455, 2025). "The DLL4-NOTCH2 axis critically regulates tumor progression through vascular and immune modulation." (PMID 41326912, 2025). "However, the combination of anti-DLL4 and anti-PD-1 antibodies strongly inhibited tumor growth in TTN-KO TNBC tumors, leading to a complete response in up to 75% of cases." (PMID 41326912, 2025). "In addition, As2O3 treatment in vitro and in vivo resulted in dose-dependent decreased expression of HIF-1α, and Dll4-Notch pathway that are involved in the regulation of tumor angiogenesis." (PMID 39717738, 2024).
tumor (continued). "The vaccine induced the production of anti-DLL-4 antibodies, which disrupted tumor vasculature without causing endothelial cell death, leading to non-productive tumor angiogenesis." (PMID 39081320, 2024). "Interestingly, the DEG enrichment of JAG1, DLL4, and all Notch receptors increased according to tumor stage." (PMID 39074091, 2024). "DLL4-blocking antibodies resulted in excessive, dysregulated angiogenesis and the formation of abnormal blood vessels that were ineffective at transporting nutrients, thereby inhibiting tumor growth in preclinical models." (PMID 38672496, 2024). "Despite prior studies indicating that DLL4 regulates tumor dormancy while, mesothelial cell-derived Jagged2 forms a juxtracrine loop with the Notch receptor expressed by OvCa cells and regulates tumor growth and adhesion." (PMID 38575576, 2024). "A recent study on DII4-induced Notch signaling in EC growth and development shows that antibodies against Dll4 and VEGF had strikingly different effects on tumor blood vessels, suggesting differing mechanisms underlying Notch- and VEGF-mediated tumor angiogenesis." (PMID 38580870, 2024). "Interestingly, the anti-tumor effect of Dll4-blockade was potentiated by combinatorial inhibition of VEGF signaling further providing potential anti-cancer therapeutic opportunities." (PMID 38269089, 2023). "Notably, Dll4 is highly expressed on the surface of tumor vascular endothelial cells as a ligand of the Notch receptor." (PMID 37292204, 2023). "Given the specificity of Dll4 expression in endothelial cells (ECs), targeting this ligand was initially thought to be an effective and safe strategy for specifically modulating Notch signaling and angiogenesis in disease, such as during tumor growth." (PMID 37745941, 2023). "Interestingly, CAF states 2 and 3 (inflammatory/adipogenic CAFs) were shown to mediate crosstalks with tumor endothelial cells notably via NOTCH1/2/3_JAG1/2/DLL4 pathways reiterating the role of NOTCH signaling in CAF-mediated angiogenesis." (PMID 38269089, 2023). "However, while in physiological conditions Dll4 selects the Tip cell only, activating the Notch pathway, in tumor-induced angiogenesis Dll4 expression was observed in the majority of tumor vessels." (PMID 37371466, 2023). "DLL4 inhibition decelerates tumor growth by deregulating angiogenesis." (PMID 38155938, 2023). "Thus, the rationale to inhibit DLL4–Notch1 signaling appears paradoxical as its inhibition decreases tumor growth by triggering excessive but poorly perfused tumor vessels." (PMID 36376768, 2023). "Our findings also suggest that the vascular structure abnormalization, rather than neoplasms, causes the reported anti-Dll4 antibody toxicity." (PMID 37745941, 2023). "Moreover, the authors try to seek any correlation between Dll4 and cancer stem cells in tumor development." (PMID 35406423, 2022). "IFNγ-γ-mediated vascular inhibition is one of the important anti-tumor mechanisms of T cells, as it can reduce the expression of Dll4 signaling pathway in endothelial cells, destroy the connection between endothelial cells, and resist angiogenesis in tumor tissue." (PMID 35734400, 2022). "Dll4 inhibition regulates cancer stem cells frequency and suspends tumor growth." (PMID 35406423, 2022). "Interestingly, overexpression of Dll4 also affects tumor vasculature, leading to reduced tumor growth, supporting the notion of the importance of dosage sensitivity in the Notch pathway." (PMID 35682918, 2022). "Since DLL4 expression could potentially be blocked through the DLL4-Notch pathway, it could act as a therapeutic target to suppress tumor growth and angiogenesis in NPC." (PMID 35565251, 2022). "In a more recent study, tumor metastasis was also reported to be altered by deregulation of Dll4." (PMID 35406423, 2022). "As ligands of the NOTCH receptor, JAG1 and DLL4 levels were analyzed in the PDAC tumor tissues." (PMID 35673567, 2022).
tumor (continued). "In addition to VEGF, the Notch pathway’s essential ligand delta-like ligand 4 (DLL4) plays a key role in tumor neo-angiogenesis and regulates the VEGF pathway’s signaling to prevent excessive vascularization." (PMID 36389699, 2022). "In humans, VEGF and DLL4 are strongly co-expressed in tumor tissues." (PMID 36428773, 2022). "Similarly, DLL4 blockade decreases tumor growth as DLL4 inhibition increases the density of poorly functional vascular sprouts and branches, inducing disordered tumor vessels." (PMID 36428773, 2022). "Therefore, DLL4 has also emerged as an attractive target for antiangiogenic cancer therapy and provides an additional level of control for blocking tumor growth." (PMID 35673577, 2022). "Overexpressed DLL4 in ECs could activate Notch in tumor cells, which further accelerate angiogenesis of tumor cells." (PMID 34476005, 2021). "Given the ability of DLL4 to regulate tumor angiogenesis, strategies that target Notch/DLL4 signaling may show therapeutic potential against cancers." (PMID 33681228, 2021). "Furthermore, endothelial DLL4-mediated Notch signaling supports tumor cell invasion due to an increased MMP-9 expression by ECs." (PMID 34073394, 2021). "Many proangiogenic factors are upregulated in tumor cells and tumor-associated stromal cells, including vascular endothelial growth factor (VEGF), fibroblast growth factor (FGF), and delta ligand-like 4 (Dll4)." (PMID 34966744, 2021). "DLL4 represents an attractive target for cancer therapy since the blockade of DLL4/Notch signaling has been shown to cause non-productive tumor angiogenesis, to reduce the growth of VEGF-sensitive and resistant tumors, and to affect the CSC pool." (PMID 34680255, 2021). "However, vessels that result from Dll4-Notch inhibition are excessively disorganized and poorly perfused, which (somewhat unexpectedly) reduces tumor size." (PMID 34692672, 2021). "Moreover, a number of MEF2 targets have been identified, namely related to cancer (e.g., MYC, TGFB1, CARD11, RHOB, and NDRG1), and particularly with sprouting angiogenesis in tumor vascularization (e.g., Delta-like ligand 4, Dll4)." (PMID 33673112, 2021). "It is unclear whether tumour cell-derived Dll4 exploits this organ-specific angiogenic mechanism to facilitate BM vessel remodelling." (PMID 34836954, 2021). "Moreover, endothelial Delta-like 4 (DLL4), which is important for controlling blood vessels formation through activating Notch1 receptors, can bind to Notch3 receptors on tumor cells to support their survival." (PMID 34073394, 2021). "DLL4-Notch signaling activity in tumors enhances blood vessels' better perfusion (productive vessels), stimulating tumor growth despite the reduced vascular density and improving function within a tumor." (PMID 36643842, 2021). "In addition, treatment with anti-human DLL4, alone or in combination with irinotecan, delays tumor recurrence and reduces the frequency of CSCs, as demonstrated by the limiting dilution assay and in vivo tumorigenesis studies." (PMID 33806312, 2021). "If, as we propose, Dll4-Notch signaling promotes EC commitment to limit (partial or complete) EndoMT, therapies that activate Notch signaling specifically in tumor vasculature may help suppress pathological angiogenesis." (PMID 34692672, 2021). "The angiogenesis of functional capillaries plays a crucial role in tumor development, and it has been reported that the expression of DLL4 could be regulated by vascular endothelial growth factor (VEGF) on vascular endothelial cells." (PMID 34638298, 2021). "Interestingly, ALDH1A1+ BCSCs that co-expressed Notch1 showed direct contact with the tumor endothelium that expressed DLL4 in a tumor arteriole." (PMID 34168243, 2021). "Oon suggested the role of Dll4 in Jagged1-induced tumor angiogenesis and tumor growth." (PMID 34666595, 2021).
tumor (continued). "MMGZ01, a novel human DLL4-specific monoclonal antibody, was found to inhibit tumor growth through various mechanisms, namely inhibition of tumor cell proliferation, promotion of tumor cell apoptosis and reduction in the cancer stem-like cell population, leading to the reversal of EMT." (PMID 33198378, 2020). "DLL4 blockade has been shown to inhibit tumor growth and angiogenesis in some murine tumor models." (PMID 32742191, 2020). "By overlaying dark field imaging of NPs with immunofluorescent imaging of tumor blood vessels, we found marked differences in intratumoral distribution of NPs in tumors growing in the SS.BN3IL2Rγ- host (low-DLL4) compared with the SSIL2Rγ- host (high-DLL4)." (PMID 32373218, 2020). "To date, few studies have reported on the effect of DLL4 on the RT sensitivity of tumor cells." (PMID 32742191, 2020). "DLL-4 antibodies have also been utilised previously to target CSCs in colon tumour xenografts, which led to a reduction in tumour growth, and the delay in tumour initiation and tumour recurrence." (PMID 32575680, 2020). "However, little is known about the effects of a combination of ABL001, targeting dual antigens VEGF and DLL4, and chemotherapy on tumor vessels and tumor cells in xenograft models compared to each monotherapy alone." (PMID 33383646, 2020). "In the case of general xenograft models using human cancer cell lines, we used the mouse surrogate version of ABL001 (mABL001: binding to human VEGF and mouse DLL4) for the studies, as DLL4 is expressed by mouse endothelial cells involving tumor angiogenesis in tumor xenografts." (PMID 33383646, 2020). "Several preclinical xenograft studies have demonstrated that DLL4/Notch blockade inhibited tumor progression by promoting hyperproliferation of endothelial cells, which resulted in an increase in vascular density and a decrease in functional tumor vasculature." (PMID 33383646, 2020). "It has been suggested that Delta-like 4 (Dll4) expressed on endothelial cells may play an activating role in promoting T-ALL in a tumour model system in mice that revealed the roles of Dll4 in mediating T-ALL release from tumour dormancy." (PMID 32210034, 2020). "Such a rapid reduction of DLL4 expression after mABL001 caused some tumor vessels to be stained only by CD31 but not by DLL4." (PMID 33383646, 2020). "Here, we demonstrated using ex vivo 3D microCT images that vascular structure, density, and thickness of vasculature differ in the SS.BN3IL2Rγ- host (low-DLL4) compared with the SSIL2Rγ- host (high-DLL4), which was further supported by immunofluorescence imaging of tumor sections." (PMID 32373218, 2020). "In summary, our results suggest that DLL4 expressed by tumor microenvironment could activate Notch signaling in CLL." (PMID 31616059, 2020). "In addition, miR-30a-5p was shown to decrease tumor microvessel density, by targeting endothelial DLL4, which is enrolled in tumor angiogenesis." (PMID 32487203, 2020). "In tumour angiogenesis, interfering with DLL4/Notch signalling leads to reduced neoplastic growth, partially due to excessive EC tip cell formation and sprouting, ultimately resulting in poorly perfused and non-functional vessels not capable of sustaining efficient tumour growth." (PMID 32506201, 2020). "Dll4 has been found in exosomes formed from tumor endothelial cells." (PMID 33198378, 2020). "Chemotherapy or radiotherapy in combination with mAb against DLL-4 promoted tumor necrosis." (PMID 30917608, 2019). "Using different experimental models and a variety of genetic and pharmacologic approaches, several studies report that the DLL4/NOTCH pathway is a critical negative regulator of tumor angiogenesis, acting to restrain excessive VEGF-induced vascular sprouting and angiogenesis." (PMID 30691003, 2019).
tumor (continued). "Previous studies showed that altered expression of Notch ligands could underlie immunosuppression in cancer, and in particular, expression of Delta-like ligands DLL1 and DLL4 was significantly down-regulated in tumor-bearing hosts." (PMID 30940183, 2019). "On the other hand, E2F7/8 suppresses tumour angiogenesis via the induction of DLL4." (PMID 31878977, 2019). "It is known that both DLL4 and Ang-1 play key roles in tumor angiogenesis." (PMID 31839752, 2019). "In particular, Dll4 represents a potential biomarker and therapeutic target in OC, a type of tumor characterized by strong angiogenesis and showing Nova2 upregulation selectively in the tumor vasculature." (PMID 31771184, 2019). "Jagged-1 has been proven to participate in multiple aspects of cancer biology including neoplastic cell growth and the metastatic process, promoting cancer stem cells and resistance to therapy, while Dll-4 has been proven to participate in the main procedure of tumor angiogenesis." (PMID 30111989, 2018). "Interestingly, it has recently been discovered that tumor-derived exosomes contain Dll4 and can thus modulate vessel development in distant recipient cells, providing a new aspect to Notch signaling that does not require direct cell-to-cell contact." (PMID 29922170, 2018). "Both Delta-like 4 (DLL4) and Jagged1 (JAG1) ligands are implicated in tumour angiogenesis." (PMID 28445154, 2017). "In vivo, DLL4 silencing inhibited the tumor formation ability of GCSPCs." (PMID 27891816, 2017). "Moreover, given Dll4 plays an important role in pericyte formation during tumor vessel expansion, the extent of pericyte coverage were examined after Dll4 siRNA treatments." (PMID 28284219, 2017). "In addition, considering the accessibility of the tumor endothelium, therapeutic Dll4 delivery to the neoplastic cells seems much more complex to implement than endothelial targeting." (PMID 28288569, 2017). "We found that ubiquitous and endothelial-specific Dll4 blockade led to a similar phenotype in the small and large intestine, but a stronger effect on tumor initiation was observed in the small intestine and a greater impact on tumor growth was seen in the large intestine." (PMID 28086833, 2017). "Alternatively, we explored the endothelial Dll4 overexpression using different mouse tumor models." (PMID 28288569, 2017). "Targeted Dll4 allele deletion, local overexpression of Dll4/Notch-blockers, systemic application of soluble Dll4/Notch-inhibitors and DNA vaccination were found to result in a significant suppression of tumor growth in numerous preclinical models, including malignancies resistant to VEGF inhibitors." (PMID 28288569, 2017). "Indeed DLL4/Notch inhibition has been shown to reduce tumor growth by producing an excess proliferation of immature vessels and so deficient vascular perfusion." (PMID 28533486, 2017). "Dll4 also appeared in other tumor cells, besides goblet cells." (PMID 28086833, 2017). "In particular, we aimed to assess whether an effect of Dll4 signalling on the ApcMin/+ tumor stem cells was solely a consequence of its action on tumor angiogenesis or if other, more direct, mechanisms might be involved." (PMID 28086833, 2017). "Dll4 and Jagged1 may have opposing effects on tumor angiogenesis but a uniform prognostic effect in GBM." (PMID 28157712, 2017). "In summary, this study suggests that endothelial Dll4 overexpression may constitute an effective mean to suppress tumor angiogenesis, neoplasm growth and metastasis formation, without observed toxic side effects." (PMID 28288569, 2017). "The effect of DLL4 silencing on tumor formation ability in vivo was evaluated." (PMID 27891816, 2017). "In line with a role of Notch3 in tumour associated endothelial cells, we observed an increase in CD31 and DLL4 expression in tumours from Notch3LacZ/LacZ mice, but no change in αSMA or PDGFRβ (Beta-type platelet-derived growth factor receptor), two pericyte markers." (PMID 28719575, 2017).